SMO (smoothened, frizzled class receptor)
Diseases named in the same sentence as SMO in open-access papers (continued):
Sharing a sentence is not in itself a finding about the gene and the disease.
tumor (continued). "Similarly, another SMO inhibitor, LDE-225, and a BMP4 blocking antibody were used in the co-culture system (with SKOV3 and CAOV-3 tumor cells) and both demonstrated a reduction in CA-MSC derived BMP4 and tumor derived HH." (PMID 26755648, 2016). "With IVA, there was four bone-related processes brought front only in the case of the tumour tissue—“myelopoiesis of bone marrow” (NPM1, RARA), “quantity of trabecular bone” (CREBBP, SMO), “outgrowth of bone marrow cells” (ALK) and “inflammatory response of bone marrow-derived macrophages” (RELA)." (PMID 25496518, 2014). "Amplification of SMO was found in one tumor, but this tumor did not exhibit elevated expression of SMO or GLI1." (PMID 24368541, 2013). "Because eRMS is one of the three major tumor types that develop in Ptch1+/− mutant mice and the other two tumor types (BCC and medulloblastoma) have shown response to SMO inhibition in vivo, it was assumed that targeting the Hedgehog pathway would have utility in eRMS." (PMID 22619564, 2012). "In addition, knockdown of SMO by SMOshRNA prevented the growth of HT29 cells in SCID mice, while wt HT29 subcutaneous xenografts responded to cyclopamine by reduction in tumor volume." (PMID 20957031, 2010). "Both tumour weight and tumour volume showed significantly moderate correlations (r = 0.3297) and strong correlation (r = 0.5609), respectively, with SMO expression, while HER2 expression level exhibited no obvious correlation with tumour weight or tumour volume." (PMID 40426308, 2025). "All tumor types had significantly higher SMO expression than non-inflamed stroma (Kruskal-Wallis test, P < 0.001, with post hoc pairwise comparisons using Dunn’s test P < 0.001 for stroma vs. BCC, P < 0.001 for stroma vs. SCC, and P < 0.001 for stroma vs. SEB)." (PMID 40542075, 2025). "Combination treatment in vitro was significantly more effective in inhibiting tumor growth and SHH activation than either SMO and DNMT1 inhibitors alone, and this synergistic effect was seen in both murine and human cell models of SHH-MB sensitive to SMO inhibitors." (PMID 39107797, 2024). "In particular, in vitro and in vivo RMS models have shown that SMO inhibitors are not always effective and may even promote tumour progression in some cases." (PMID 36765685, 2023). "However, GLI1 inhibition didn’t correlate with tumour responses, pointing at GLI1 as a good pharmacodynamic marker for SMO inhibitors but not for tumour response." (PMID 36765685, 2023). "Conversely, the lack of the same mutation in cfDNA from patient #3 may be ascribed to the presence of not-tumor cfDNA confirmed by the presence of the p.Pro61Ala in the SMO gene (at an AF of 50%), as evidenced by the WES on PBMC of this patient." (PMID 36901733, 2023). "Beyond the use of SMO inhibitors, GLI inhibitors (such as GANT61), may have potential in tumours that express high levels of these proteins and may have a broader range of indications since they may function regardless of the presence of Hh-activating mutations." (PMID 36765685, 2023). "Indeed, despite the fact that hypoxia triggered Hh-mediated tumor stromal interactions and increased sonic secretion, the authors did not observe any effects on SMO and GLI1 expression." (PMID 36230699, 2022). "Similarly, the lncRNA LINC01133 may regulate the activity of tumor suppressor pathways by dysregulating ACTL6A, SMARCD2, SMO, PHC3, and CENPP." (PMID 34925461, 2021). "However, by Sanger sequencing, we did not detect mutations at the established hotspots in AKT1, SMO, KLF4 and TRAF7, suggesting different tumor drivers acting in this age group." (PMID 34495383, 2021). "Mutations within the components of the HH pathway, for example, membrane receptor proteins PTCH1 and SMO, non-membrane receptor proteins, such as SUFU and REN (KCTD11), disrupt the feedback loop causing activation of HH pathway and tumor progression." (PMID 33637972, 2021).
tumor (continued). "atients’ selection based upon an inadequate marker of HH pathway activation may therefore contribute to the lack of clinical efficacy of SMO antagonists in various neoplasms." (PMID 32879407, 2020). "This may explain the overall lack of anti-tumor therapeutic efficacy of HH inhibitors, most of which target SMO activity." (PMID 32879407, 2020). "We speculate that patients’ selection based upon an inadequate marker of HH pathway activation may therefore contribute to the lack of clinical efficacy of SMO antagonists in various neoplasms." (PMID 32879407, 2020). "Henceforth, changes observed in the behavior of Luminal A cell lines treated with Hh inhibitors did not correlate with suppression of GLI1, PTCH1, and SMO transcripts, thus changes observed in tumor cell behavior are likely the result of off-target effects or non-canonical Hh signaling mechanisms." (PMID 31658643, 2019). "In the absence of activated FGFRs, SMO signaling may thus contribute to tumor cell dissemination and accelerate expansion and spreading of the tumor independent of its growth-promoting functions." (PMID 31835472, 2019). "GLI1 inhibitors, like GANT61, may have a much broader indication than SMO inhibitors because GLI1 is expressed in many tumour cells that do not have an active HH pathway." (PMID 30068568, 2018). "Further clonal formation assay indicated the most dramatic inhibitory effects of SMO inhibitors on clonogenicity of A549 and H1299 cells, in which clonal formation rates were reduced more that 70% for BMS only and more than 90% for BMS plus GDC in those tumor cells with 24 hours’ exposure." (PMID 28507311, 2017). "Taken together, our data suggest that upstream SMO inhibitors may not prove efficacious in tumours where a proportion of cells activate GLI via EMT-TFs and instead argue that inhibitors directly targeting GLI may be more effective." (PMID 28604738, 2017). "Given that the viability of A549 and H1299 was slightly affected with exposure to SMO inhibitors GDC and BMS alone, here we tested whether any potential additive or even synergistic effects of SBE with one of those two compounds on tumor cell proliferation were experimentally significant." (PMID 28507311, 2017). "Likewise, several receptor genes (e.g. IL4R, INFAR/INFGR, PTCH/SMO) were consistently expressed by tumor cells and/or TAMs, but ligand expression was not detectable." (PMID 27215396, 2016). "Knockdown of both SMO and GLI1 in SSM2c and A375 melanospheres and engraftment of SSM2c cells transduced with lentiviral-shSMO and LV-ShGLI1 leads to a drastic decrease in the fraction of ALDH+ cells, reduced clonogenicity and reduced tumour growth, respectively." (PMID 26270676, 2015). "Although both treatments dramatically reduced tumor invasion and reversed EMT progress induced by hypoxia, GLI1 siRNA could not interrupt the hypoxia-mediated increase in SMO; conversely, blocking SMO function by cyclopamine decreased the expression of the transcription factor GLI1." (PMID 23786654, 2013). "However, such an approach has proven challenging because even though Ptch1+/− mouse tumors depend on Smo for RMS initiation, the SMO inhibitor cyclopamine does not appear to suppress tumor growth in vivo." (PMID 22619564, 2012). "Tumours could not develop because the active SMO needed cilia to initiate the Hh pathway." (PMID 39234399, 2024). "Therefore, it is important to carry out an exhaustive molecular study of the Hh pathway in tumours that do not respond to SMO inhibitors, but that show a strong dependency on Hh ligands, in order to find new molecular targets and an effective way to target them." (PMID 36765685, 2023). "Moreover, PDX tumours were more sensitive to growth inhibition by GANT61 versus IPI926 under this treatment regimen, suggesting that targeting GLI may be more efficacious than targeting SMO." (PMID 28604738, 2017).
tumor (continued). "However, our findings indicate that, while bulk tumor and/or stromal cells may respond to SMO inhibitors, the tumor-initiating stem-like cells may not respond, possibly allowing for tumor resistance and recurrence." (PMID 25252859, 2014). "To summarize, SMO, GLI, Hh-FOXM1-TPX2, and non-canonical hedgehog activation via TGF-β-1/SMAD 3 are involved in hepatocarcinogenesis and tumor growth." (PMID 38730691, 2024). "Consistently, genetic silencing or pharmacological inhibition of GLI1, but not of SMO, reduces LAC tumor growth and stemness in vitro and in vivo." (PMID 31244888, 2019). "Irrespective of tumour type, 36 patients were reported experiencing grade 3/4 DLT when receiving SMO inhibitors." (PMID 31362788, 2019). "Examination of Hh transcripts indicate that tumor growth suppression correlates with down-regulation of GLI1, PTCH1, and SMO transcripts in cells of mouse but not of human origin." (PMID 31658643, 2019). "We also determine that tumors arising from Gαs pathway inactivation are independent of the canonical Hedgehog regulators SMO and GPR161 and establish the Gnas-eKO and PKI models as a unique resource to understand tumor formation arising from noncanonical activation of Hedgehog signaling." (PMID 40060632, 2025). "Several studies documented the lack of efficacy of SMO inhibitors, alone or in combination with chemotherapy, in a range of tumours, even though in some cases, a reduction in GLI1 expression levels was observed in tumour tissues." (PMID 30068568, 2018). "Thus, in tumours cells lacking PTCH1, SMO is constitutively active and HH pathway activity remains elevated." (PMID 30068568, 2018). "However, the authors reported that while PI3 K inhibitors appeared to prevent the development of resistance to the SMO inhibitor LDE-225, they were not able to inhibit the growth of established tumours." (PMID 30068568, 2018). "The emerging consensus seems to be that, while such tumours may be targeted by agents that inhibit GLI1, such as GANT61, they are not sensitive to treatment with physiological levels of SMO inhibitors." (PMID 30068568, 2018). "Here, we report the synergistic effect of GDC-0449 and Dox only in SMO-positive cells (BxPC-3, Panc-1, and MIAPaca-2), but not in SMO-negative SW1990 cells, thereby suggesting that the effect of GDC-0449 also relied on SMO expression in tumor cells of individual patients." (PMID 29042665, 2017).
cancer (268 papers, 2009 to 2026). A tumor composed of atypical neoplastic, often pleomorphic cells that invade other tissues. "Smoothened (SMO), a member of the G-protein-coupled receptor superfamily, mediates Hedgehog signaling and is linked to cancer and birth defects." (PMID 41811180, 2026). "We observed the L412F mutation in SMO, a known cancer hotspot that likely confers a GOF oncogenic effect via aberrant Hh pathway activation." (PMID 40725190, 2025). "These mutations enable cancer cells to proliferate independently of HH signalling, evading SMO inhibitors like LDE-225, GDC-0449, and LEQ-506." (PMID 39568072, 2024). "These molecules are second-generation SMO inhibitors that target components downstream of SMO and can be efficacious for the treatment of cancers linked to the GLI aberrant activation, including BCC." (PMID 37947611, 2023). "There are many possible explanations for the clinical failure of SMO inhibitors outside mutation-driven cancers." (PMID 36765685, 2023). "SMO is an important molecule in the Hh pathway that is highly expressed in many types of cancers, including HCC, and is associated with poor prognosis and good cancer progression 57,58." (PMID 37151886, 2023). "Aberrant activation of the Hh pathway, especially the Hh and SMO proteins, has been reported to be associated with cancer progression and metastasis in HCC 33,57,58,60,61." (PMID 37151886, 2023). "It is worth noting that the mutation frequency of SMO was the highest in these cancers, and the MSI score and the MSI-H proportion were higher in the SMO_MUT group in these three cancers compared to the wild type." (PMID 36405701, 2022). "We compared the TMB level, NAL, MSI score, and DDR gene mutations between tumors carrying SMO mutations and those that are SMO wild type in the TCGA pan-cancer cohort to investigate the underlying mechanism linking SMO mutation to ICI response." (PMID 36405701, 2022). "Our study first demonstrated that the SMO mutation status is an independent prognostic factor for predicting the efficacy of ICIs in patients with cancer." (PMID 36405701, 2022). "Type I cancers arise independently of the ligand due to activating mutations in SMO or inactivating mutations in PTC or SUFU." (PMID 36294790, 2022). "Mutations in SMO that lead to constitutive activation play a role in carcinogenesis of various cancers." (PMID 35281856, 2022). "The SMO mutation status is an independent prognostic factor that can be used to predict better clinical outcomes of ICI treatment across multiple cancer types." (PMID 36405701, 2022). "Since the mechanisms underlying resistance to SMO inhibitors are elucidated, several approaches have been attempted to overcome the resistance in cancer treatment." (PMID 35163655, 2022). "As mutations in Patched1 or SMO can result in aberrant Hh pathway activation, SMO is often a target of the Hh pathway inhibitors in cancer therapeutics." (PMID 34572947, 2021). "For example, mutations in PTCH1 and SMO were found to be mutually exclusive in the MB SHH cancer type." (PMID 34615983, 2021). "Aberrant expression of SHH has been linked to the initiation and progression of numerous cancers, and HH inhibitors targeting SMO are in the clinic against basal cell carcinomas." (PMID 34887403, 2021). "Although GLI1 expression has been frequently associated with poor prognosis in many known cancers, SMO inhibitors are ineffective in treating various cancers despite showing antitumor activity in preclinical studies." (PMID 34572373, 2021). "This method of GLI regulation is commonly implicated in cancers that are resistant to SMO inhibitors (e.g., cyclopamine and vismodegib)." (PMID 34572373, 2021). "The activity of SMO must be very well balanced by these different mechanisms in vivo because the malfunction of SMO will not only cause developmental defects in early stages, but also induce cancers in late stages." (PMID 34440907, 2021).
cancer (continued). "Cancer cells can acquire resistance to SMO antagonists through secondary mutations in the SMO receptor, following drug administration." (PMID 34164380, 2021). "Inactivation of the PTCH1 gene (73%) is known as inactivation of the tumor suppressor gene in BCC, and other cancer-related gene mutations that cause BCC carcinogenesis include SMO activation mutations and negative regulators of the Hh pathway." (PMID 33066274, 2020). "RARA, SRC and SMO can also potentially be used as diagnostic, prognostic and/or therapy-response biomarkers in cancer." (PMID 32099096, 2020). "This pathway is physiologically responsible of the normal development of the embryo, but in patients with Gorlin-Goltz syndrome PTCH mutations cause uncontrolled signaling through SMO, with high rates of cancer, especially BCCs." (PMID 32545245, 2020). "It has also been shown that SMO is upregulated in cancer-associated fibroblasts (CAF), the predominant stromal cell type, comparing with normal pancreatic fibroblasts." (PMID 32962123, 2020). "The prediction that the only Wnt capable of binding to SMO with at least moderate affinity is Wnt3a is quite interesting, considering that both of these proteins are implicated in numerous cancer types, albeit studied in distinct signalling contexts." (PMID 31454915, 2019). "Smoothened (SMO) is also frequently mutated in cancers arising at the colon, central nervous system, and many other cancers types." (PMID 31072060, 2019). "In other FZD paralogs or SMO, mutation of R6.32 to H, C, Q, and S is associated with different forms of cancer." (PMID 30737406, 2019). "Several studies demonstrated that a number of gain-of-function mutations of SMO are implicated in the pathogenesis of cancers such as BCC and MB." (PMID 30558232, 2018). "The identification of the IL6/JAK/STAT3 signaling cascade as cooperative partner in HH/GLI‐associated cancers provides a new rationale for evaluating combined HH‐IL6 targeting in BCC to improve the therapeutic efficacy of SMO inhibitor treatments." (PMID 29987839, 2018). "We propose that small molecule inhibition of DYRK1B represents a novel and promising approach to target HH/GLI-associated cancers including malignancies with acquired or de novo resistance to SMO inhibitors." (PMID 26784250, 2016). "The results support the use of DYRK1B antagonists for the treatment of HH/GLI-associated cancers where SMO inhibitors fail to demonstrate therapeutic efficacy." (PMID 26784250, 2016). "The discovery of specific, small molecule antagonists of SMO has established new options for the targeted therapy of human cancers associated with Hh signaling." (PMID 23303278, 2013). "Hh-ligand-independent activation of GLI1 expression via loss of PTCH or oncogenic mutations in SMO have been reported for a number of cancers and pharmacological inhibition with SMO-directed inhibitors shown to block Hh signalling and cell proliferation." (PMID 21505458, 2011). "Additionally, higher SMO levels were linked to greater proliferative activity, reflected by a higher Ki67 hot-spot index across all three carcinomas and by a positive correlation with mitotic count in BCC, whereas no such correlation was found in SCC or SEB." (PMID 40542075, 2025). "In addition, mutations of PTCH1 and SMO are found in other types of cancer, where hedgehog signaling is activated in the epithelial cells (cancer cells)." (PMID 36864465, 2023). "Analogously, secondary resistance to SMO inhibitors in cancer treatment may come from SMO mutations." (PMID 35163655, 2022). "We further investigated whether the survival benefit exist in ICI-treated patients carrying SMO mutations in the pan-cancer cohort." (PMID 36405701, 2022). "Our in vitro results indicated that SMO mutations could induce the expression of PD-L1 and promote the growth of cancer cells." (PMID 36405701, 2022).